SIRT1 (sirtuin 1)
Diseases named in the same sentence as SIRT1 in open-access papers (continued):
Sharing a sentence is not in itself a finding about the gene and the disease.
metabolic disorders (continued). "Similarly, hypermethylation of the SIRT1 gene (encoding the Sirtuin 1, a deacetylase whose downregulation has been found in many disease conditions) correlates with lower transcript levels and with an increased risk of inflammatory and metabolic diseases." (PMID 36711387, 2022). "Sesamol counteracts on metabolic disorders of middle-aged alimentary obese mice through regulating skeletal muscle glucose and lipid metabolism, which might be associated with the stimulation of the SIRT1/AMPK pathway." (PMID 35382382, 2022). "For future studies, it would be interesting to explore whether NF-κB activation in the hypothalamus, by over-nutrition, is accompanied by a decrease in SIRT1 and whether it may be the cause of metabolic dysregulation in other organs, thus leading to metabolic diseases." (PMID 32485811, 2020). "Therefore, impaired SIRT-1 expression and activity could be associated with the metabolic disorders observed in the OF group at adulthood." (PMID 29018245, 2017). "SIRT‐1 and NF‐ᴋB exhibit an antagonistic interaction in regulating inflammatory responses and metabolic disorders." (PMID 40903907, 2025). "SIRT1 activation is known to support mitochondrial biogenesis and protect against metabolic disease." (PMID 41154064, 2025). "The AMPK/SIRT1/PGC‐1α pathway forms a coordinated regulatory network that improves metabolic disorders through multiple mechanisms." (PMID 41268687, 2025). "The activation of the NAMPT/NAD + /SIRT1 signaling pathway has been shown to optimize bile acid composition and decrease the production of proinflammatory cytokines, thereby ameliorating metabolic disorders in MASH model animals." (PMID 40807240, 2025). "For example, Sirtuin 1 protects high-fat diet-fed mice from metabolic disorders by modulating Firmicutes and Bacteroidetes." (PMID 39917613, 2025). "Several studies have shown that activating AMPK/SIRT1 can improve metabolic disorders and ensure energy homeostasis in HFD mice." (PMID 40076847, 2025). "Each isoform has specialized functions, with SIRT1 extensively studied for its roles in aging and metabolic diseases." (PMID 40052151, 2025). "The extensive range of physiological functions regulated by SIRT1 highlights its critical role in cellular health and positions it as a potential therapeutic target for age-related diseases and metabolic disorders." (PMID 40052151, 2025). "The investigated parameters related to metabolic disorders included sirtuin 1 (SIRT-1), sirtuin 3 (SIRT-3), sirtuin 6 (SIRT-6), irisin (IRS), myostatin (MSTN), peptide YY (PYY), glucagon-like peptide 1 (GLP-1), and dipeptidyl peptidase 4 (DPP-4)." (PMID 39124846, 2024). "A growing body of evidence suggests that SIRT1 can exert protective effects in metabolic disorders and neurodegenerative diseases by inhibiting endoplasmic reticulum (ER) stress and the nuclear factor-κB (NF-κB) inflammatory signaling pathway." (PMID 38745862, 2024). "One study confirmed an opposing relationship between adipogenesis and osteogenesis via the identification of the mechanism of deacetylation of RUNX2 by Sirt-1, which is known as a major regulator of longevity and metabolic disorder." (PMID 38927789, 2024). "Several studies reported the involvement of SIRT1 in the pathogenesis, development, and treatment of different illnesses, including inflammation, cancer, and neurological and metabolic diseases." (PMID 38396635, 2024). "The accumulated evidence suggests that SIRT1 is involved in the development of endocrine and metabolic diseases." (PMID 36632457, 2023). "Studies have demonstrated the significance of the signalling pathways PI3K/AKT/mTOR, AMP-activated protein kinase (AMPK), MAPK, SIRT1, and FoXO in the control of autophagy, cell aging, and metabolic diseases." (PMID 36994671, 2023).
metabolic disorders (continued). "Sirtuin 1 (SIRT1), a nicotinamide adenine dinucleotide (NAD+)-dependent deacetylase, plays a pivotal role in regulating inflammation, oxidative stress, and metabolic disorders associated with excessive alcohol consumption." (PMID 38132956, 2023). "SIRT1 protein level was down-regulated under high fat diet conditions, which confirmed its role in metabolism disorders and circadian rhythm disruption." (PMID 37231216, 2023). "According to current research on SIRT1, this review focuses on the role of SIRT1 in endocrine and metabolic diseases." (PMID 36632457, 2023). "These evidences indicate that targeting SIRT1 has promising applications in the treatment of endocrine and metabolic diseases." (PMID 36632457, 2023). "Typical roles of SIRT1 in regulating inflammation, metabolic disorder, apoptosis, and cell cycle regulation have been discovered." (PMID 36900446, 2023). "Studies have shown that PI3K/AKT/mTOR, AMP-activated protein kinase (AMPK), MAPK, SIRT1, FoXO, signalling pathways are important in the regulation of autophagy as well as cell aging and metabolic disorders." (PMID 36994671, 2023). "It is known that SIRT-1 affects mitochondrial function and dynamics, and as mitochondrial dysfunction characterizes many metabolic diseases, we evaluated the protein levels of PGC1-α, Mnf2 and DRP1, involved in biogenesis, fission and fusion, respectively." (PMID 36875756, 2023). "Resveratrol showed a wide range of positive effects in metabolic disorders mainly due to SIRT1 up-regulation." (PMID 37231216, 2023). "From this evidence emerges a potential role of endothelial AMPK and sirtuin-1 as promising therapeutic targets for the treatment of cardiovascular diseases e metabolic disorders." (PMID 36359402, 2022). "Because LKB1, AMPK, and SIRT1 are attractive targets for metabolic disorders, their reciprocal interactions to maintain BA homeostasis should be further elucidated." (PMID 34973477, 2022). "Emerging evidence proves that both AMPK and SIRT1 are involved in the suppression of ROS production to protect endothelial function in cardiovascular and metabolic diseases." (PMID 35883777, 2022). "A fuller and more comprehensive understanding can help us search for SIRT1 modulators with high bioavailability and specificity and provide new efficient targets for the treatment and management of endocrine and metabolic diseases, such as PCOS." (PMID 36030228, 2022). "What is the specific role of SIRT1 in endocrine, reproductive and metabolic disorders in patients with PCOS?" (PMID 36030228, 2022). "There are considerable data about the relationship between the Sirt1 and Nrf2 genes and metabolic diseases." (PMID 35365152, 2022). "In another study, the TR diet restored the circadian rhythm of SIRT1 expression in the liver following metabolic disorders." (PMID 35236328, 2022). "SIRT1 and NF-κB have antagonist crosstalk in regulating inflammatory responses and metabolic disorders." (PMID 34656137, 2021). "Resveratrol treatment in mouse models has been seen to protect against metabolic disease by activating SIRT1 and PGC-1." (PMID 34552688, 2021). "Taken together, these data highlight the decreased expression and activity of SIRT1 as a key component of the molecular mechanisms that participate in the process of aging, neurodegenerative and metabolic diseases." (PMID 34616289, 2021). "Previously, studies have reported that metformin can activate SIRT1 to improve renal outcomes, owing to the SIRT1 involvement in the pathogenesis of age-dependent and metabolic diseases." (PMID 33815878, 2021). "Other studies have revealed that Plin5 can reduce FFA-induced metabolic disorders and inflammation, mainly because Plin5 relies on sirtuin 1 to promote autophagy." (PMID 34638947, 2021). "SIRT1 is also involved in cross-generational metabolic diseases and protection against MetS-related symptoms." (PMID 33806509, 2021).
metabolic disorders (continued). "Sirt1 suppression has been characterized as a contributing factor in metabolic disorders and various cardiovascular diseases." (PMID 35096293, 2021). "Researchers found that it can increase the expression and activity of SIRT1, improve the quality and function of mitochondria, and prevent mitochondrial dysfunction and metabolic disorders in obese mice induced by a high-fat diet." (PMID 34616289, 2021). "SIRT1 has in fact been validated as a target against metabolic disease, and several SIRT1 activators have been developed, such as the well-known drug resveratrol." (PMID 33806509, 2021). "SIRT1 levels in offspring of maternal HFD-fed mice are reduced in the adipose tissues, suggesting a role for SIRT1 in cross-generational metabolic diseases." (PMID 33806509, 2021). "Our previous study also indicated that salidroside resists metabolic disorders in skeletal muscle via upregulating SIRT1-mediated mitochondrial quality control in mice." (PMID 33935745, 2021). "As a small molecule activator, SRT-1720 can specifically increase the expression level of SIRT-1, regulate the energy metabolism efficiency of body tissues, and prevent metabolic disorders." (PMID 34315467, 2021). "Nicotinamide adenine dinucleotide (NAD +) dependent class III histone deacetylase (SIRT1) has been dubbed as the “longevity gene”, which can effectively resist aging, various tumors, cardiovascular diseases, and metabolic diseases." (PMID 34320994, 2021). "It has also been shown that antagonistic crosstalk between sirtuin-1 (SIRT1) and NF-κB in the regulation of inflammation and metabolic disorders." (PMID 33705621, 2021). "Activated SIRT1 deacetylates and regulates its downstream targets, performing various beneficial functions in metabolic disorder‐related vascular disease." (PMID 32286000, 2020). "In recent years, the anti-aging gene SIRT1 has been identified as an important metabolic gene that is critical to prevent metabolic diseases and neurodegenerative diseases." (PMID 32461378, 2020). "Preclinical and clinical studies in the treatment of complex and inherited metabolic diseases have produced contrasted results in the evaluation of health benefits of activation of Sirt1 by natural and pharmaceutical small activating molecules." (PMID 32796716, 2020). "There are seven members of the mammalian Sirtuins (Sirt1-Sirt7), among which Sirt1 is the most studied and has been implied to play an important role in the pathogenesis of metabolic diseases like DKD." (PMID 31828168, 2019). "Evidences gathered from a variety of species have indicated that resveratrol provides certain benefits by activating Sirt1, such as improving mitochondrial function and ameliorating both aging and metabolic disorders." (PMID 29713468, 2018). "Deficiency of Sirtuins (SIRT1, SIRT6, and SIRT7) is associated with shortened lifespan and metabolic diseases." (PMID 30574122, 2018). "Accordingly, in SIRT1 gain-of-function transgenic mice, SIRT1 behaves as a “thrifty gene” that protects against metabolic diseases by instructing the organism to limit energy consumption and expenditure." (PMID 30131769, 2018). "Results mainly derived from animal studies show that SIRT1 protects against or delays the onset of metabolic diseases, neurodegeneration, cardiovascular diseases, and some types of cancers." (PMID 30131769, 2018). "Resveratrol, one of the Sirt1 agonists, improves mitochondrial function and protects against metabolic disease by activating Sirt1 and PGC-1α." (PMID 28356158, 2017). "In that regard, resveratrol, a well-known SIRT1 activator, has been shown to confer protection against metabolic disorders by activating mitochondrial respiration and biogenesis." (PMID 28740165, 2017). "Since Resv improves mitochondrial function and protects against metabolic diseases by activating NAD-dependent deacetylase sirtuin-1 (SIRT1), the mRNA expression level of Sirt1 was also measured." (PMID 28531100, 2017).
metabolic disorders (continued). "SIRT1 is a key member of Sirtuins, playing important roles in aging and energy metabolism, which has been reported to be involved in various metabolic diseases and tumors." (PMID 29147649, 2017). "In another study, Kemper and collaborators demonstrated that activation of SIRT1 by RVT led to a reduction in acetylated farnesoid X receptor (FXR) levels in a mouse model of metabolic diseases, thereby leading to its activation." (PMID 29104258, 2017). "Daidzein can behave similarly to genistein and both of them have been shown to protect from metabolic disease in a SIRT1-dependent manner." (PMID 28425936, 2017). "RVT was described as a protective agent against several metabolic diseases and disorders mainly through the activation of SIRT1 and thereby regulating a number of important genes involved in cellular metabolic control." (PMID 29104258, 2017). "A better understanding of the central position of SIRT1 in hepatic metabolism will help in the comprehension of the metabolic diseases and will provide valuable information to prevent and treat human metabolic abnormalities." (PMID 26890260, 2016). "Some studies have revealed a significant reduction in the expression of SIRT1 in NAFLD animal models, and natural SIRT1 activator showed protective effects on metabolic diseases." (PMID 25751727, 2015). "As impair circadian rhythm contributes critically to metabolic disorders, this result suggests that SIRT1’s activity at the SCN is important for delaying the onset of metabolic dysfunction that result from impaired central control of circadian rhythm." (PMID 25805970, 2015). "The natural calorie restriction-mimetic compound resveratrol and synthetic SIRT1 activators protect against diet-induced metabolic disorders by activating both SIRT1 and AMPK." (PMID 25874615, 2015). "Studies have reported that resveratrol can improve metabolic disorders through activation of Sirtuin 1 (SIRT1) and Nrf2 expression in high fat diet-induced obese mice." (PMID 25884658, 2015). "SRT1720 was shown previously to specifically activate Sirt1 to improve metabolic disorders in obese mice." (PMID 24416337, 2014). "SIRT1 has been considered as a potential therapeutic target for a variety of diseases including metabolic disorders." (PMID 24454277, 2014). "Chronic l-leucine supplementation was shown to increase SIRT1 expression in the liver, brown adipose tissue and skeletal muscle and prevent metabolic disorders in diet-induced obese mice." (PMID 24699194, 2014). "Recently, Sirt1 has been shown that it has a critical role for beneficial effects on mitochondrial function through AMPK activation in many metabolic disease animal models." (PMID 24614171, 2014). "SIRT1 can regulate protein activation by deacetylating that plays a critical role in the pathophysiology of metabolic disorders, such as NAFLD." (PMID 25544867, 2014). "The benefit of SIRT1 activation with SRT1720 was described in vivo in metabolic diseases, leading to clinical trials of similar molecules." (PMID 24586272, 2014). "Many of the cellular processes regulated by Akt are also modulated by SIRT1: indeed, SIRT1 has been used to treat metabolic disorders characterized by aberrant Akt signalling." (PMID 24410795, 2014). "Taken together, these results suggest the use of AS101 as a novel pharmacological means to regulate metabolic disorders by increasing SIRT1 levels and activity, and interfering with T2D development and progression." (PMID 22761194, 2012). "The nicotinamide adenine dinucleotide (NAD)-dependent deacetylase (SIRT1) has been reported to be involved in protection against metabolic disorders as well as in enhancing life span." (PMID 23137106, 2012). "For example, by regulating metabolic disorders via increasing SIRT1 levels to inhibit disease progression." (PMID 22761194, 2012).
metabolic disorders (continued). "The beneficial effect of CR on aging and various metabolic disorders is dependent on the activation of SIRT1 and can be mimicked by resveratrol, a product present in grape skin and red wine, which activates the SIRT1 enzyme." (PMID 22115311, 2011). "The beneficial effects of energy restriction on lifespan and protection against metabolic disease are mediated, in part, by SIRT1 (Silent Information Regulator Transcript 1) and SIRT3 in mammals and by the SIRT1 orthologue Sir2 in lower species." (PMID 22185590, 2011). "Subsequently, elevated miR- 34a suppressesexpression of SIRT1, which then further decreases FXR activity, resulting in a viciousFXR/miR-34a/SIRT1 regulatory loop in metabolic disease states." (PMID 20689156, 2010). "We also review recent studiesshowing that the nuclear receptor FXR/SHP cascade pathway which controlsexpression of miR-34a and its target SIRT1 in normal conditions and isdysregulated in metabolic disease states." (PMID 20689156, 2010). "For example, during metabolic disorders or inflammation, both Sirt1 and PPAR‐α may be upregulated in WBCs, reflecting changes in lipid metabolism in other tissues." (PMID 40672541, 2025). "Likewise, it was connected to the regulation of expression of silent information regulator 1 (SirT1), which is a key regulator of metabolic diseases and longevity whose expression is gradually decreased in several tissues with ageing." (PMID 39920875, 2025). "Summary table of SIRT1 activators with potential to treat metabolic diseases." (PMID 41304967, 2025). "Further research into how SIRT1 glycosylation modulates its activity in liver cells, particularly in the context of metabolic diseases and fibrosis, could offer valuable insights into its role in maintaining liver health." (PMID 40052151, 2025). "SIRT1 maintains energy homeostasis by directly stimulating mitochondrial fatty acid β-oxidation genes and suppresses NF-κB signaling through deacetylation, attenuating inflammation in metabolic disorders." (PMID 40864768, 2025). "Taken together, these and other human studies strongly suggest that SIRT1 expression in circulating blood cells may represent a valuable marker for metabolic diseases." (PMID 40760244, 2025). "Notably, berberine attenuates hepatic insulin resistance through the miR-146b/SIRT1 pathway, representing a novel therapeutic target for metabolic diseases." (PMID 40864768, 2025). "Studying SIRT1 in the context of children’s health may have implications for a broader understanding of growth processes, pubertal development, metabolic disorders and nutrition." (PMID 38529393, 2024). "It is worth noting that numerous studies have revealed the critical protective role of SIRT1 in the pathological processes such as metabolic diseases and neurodegenerative diseases which is mainly due to its inhibition of ER stress and the NF-κB inflammatory pathway." (PMID 38745862, 2024). "Studying circulating SIRT1 in healthy and diseased adipose tissue may have implications for a broader understanding of fat mass metabolism and metabolic disorders." (PMID 38732001, 2024). "Moreover, in numerous studies, SIRT1 activation has been shown to regulate pathways with beneficial effects on aging and metabolic disorders, inflammatory processes, DNA damage and oxidative stress." (PMID 39062007, 2024). "In addition to the widely discussed antioxidant and anti-inflammatory effects, Citrus flavonoids were shown to play a relevant role by also hampering metabolic disorders through several other mechanisms, involving SIRT1 modulation." (PMID 38396635, 2024). "Overall, the information presents here may highlight the potential of SIRT1 as a future biomarker and therapeutic target for endocrine and metabolic diseases." (PMID 36632457, 2023). "Subsequently, we summarize the agonists/inhibitors of SIRT1 in endocrine and metabolic diseases." (PMID 36632457, 2023). "Then, we highlight the relationship between SIRT1 and endocrine and metabolic diseases." (PMID 36632457, 2023).